TNF (tumor necrosis factor)
Diseases named in the same sentence as TNF in open-access papers (continued):
Sharing a sentence is not in itself a finding about the gene and the disease.
tumor (continued). "However, recent reports demonstrate that the immunomodulatory functions of succinate are more complex, as it can suppress the secretion of the inflammatory mediators IL-6, tumours TNF-α and NO, as well as inhibit IL-1b mRNA transcription in inflammatory macrophages." (PMID 35216253, 2022). "Hyperthermia stimulates the release of tumor‐associated antigens.Hyperthermia significantly increases the proportion of mature DC subtypes (CD11c+, CD80+, CD86+).Hyperthermia increases the CD8+T number in TME.Hyperthermia increases the expression of IFN‐γ and TNF‐α." (PMID 35908281, 2022). "However, the downregulation of ANXA2 by CuO NPs might prevent tumor progression and angiogenesis via inhibition of macrophage activation and secretion of IL-1, IL-6, and TNF-α." (PMID 36362054, 2022). "results: High levels of proinflammatory cytokines (e.g., IFN‐gamma, IL‐6, TNF‐alpha) were expressed by post‐activation T cells in the presence of host tumor cells, whereas naïve T cells and post‐vaccination T cells did not express high levels of these cytokines in the presence of host tumor cells." (PMID 36222328, 2022). "Direct targeting of the TNF-α gene in Hs578T breast cancer cells increased the levels of pro-apoptotic factors, demonstrating that the modulation of various cytokines could induce tumor cell death." (PMID 36012284, 2022). "Bhlhe40 is induced by various stress stimuli, such as hypoxia, tumor necrosis factor-α, irradiation, paclitaxel, and transforming growth factor-beta (TGF-β), and participates in several pathogenic processes, including inflammation, apoptosis, tumor growth, and fibrosis." (PMID 36304536, 2022). "Additionally, TNFα is involved in tumor cell proliferation, invasion, and metastasis." (PMID 36290384, 2022). "In addition, IFN-γ and TNF-α production by ILC1s within the tumor was impaired, suggesting that the tumor-infiltrating ILC1s may be dysfunctional." (PMID 35962192, 2022). "In addition, the TNF-α levels in the tumor tissues of mice injected with ΔppGpp significantly increased, which may be one of the vital reasons for the antitumor activity of ΔppGpp (p = 0.0002 versus the control and VNP20009-treated groups)." (PMID 35847095, 2022). "EVs derived from NK cells exert tumor cell killing and inhibitory functions through four main mechanisms, including Fas/Fas ligand (FasL) pathway, perforin/granzyme pathway, tumor necrosis factor (TNF)-α pathway, and miRNA-mediated targeted regulation pathways." (PMID 35915054, 2022). "CD8+ T cells exert cytotoxic activity against tumor cells by triggering apoptotic cell death via granule exocytosis involving perforin and granzymes and via the death ligand/receptor system involving Fas ligand, TNF-α, and TNF-related apoptosis-inducing ligand." (PMID 35216272, 2022). "These included key genes associated with cytotoxic anti-tumor T cell responses (GZMA, GZMB, PRF1), co-stimulation of T cells (CD27, CD28, ICOS), and genes associated with other immune processes, including Type I IFN response (TNF, TNFSF10), as well as T cell exhaustion (CTLA4)." (PMID 36698398, 2022). "The infiltration of inflammatory cells and an environment enriched in various cytokines (TGF-β, IL-6, IL-10, granulocyte-macrophage colony-stimulating factor (GM-CSF), IL-1β, IL-23, and TNF-α) and chemokines (“chemotactic cytokines”) may be utilized by tumor cells." (PMID 36142391, 2022). "The increased expression of TNF-α in CD4+ T cells was also compounded with a significant decrease in the expression of inhibitory cytokine TGF-β in the combinatorial treatment of CT26 tumor cells when compared to single agents further confirming the immune stimulation." (PMID 36387154, 2022). "But in a pathological condition, myeloid cell precursors may be proliferated and differentiated into MDSCs that migrate to the tumor microenvironment and develop into TAMs which are induced by inflammatory cytokines, for instance, soluble tumor necrosis factor (sTNF)." (PMID 35906199, 2022).
tumor (continued). "Moreover, TNFα induces cell necroptosis and apoptosis, therefore TNFα transformed TA-MSCs may have limited ability to promote tumor growth." (PMID 33889575, 2021). "TNF-α is a typical proinflammatory factor produced during the initiation of inflammation to maintain chronic inflammation, promote the expression of other inflammatory cytokines, aggravate inflammation, and play an important role in the inflammation and tumor genesis." (PMID 34803728, 2021). "Moreover, the blockade of CD95L not only suppresses the gemcitabine-mediated tumor-promoting functions but also sensitized PDAC cells towards gemcitabine-induced cell death by diminishing the pro-inflammatory signaling of TNF-α and TRAIL in a bi- or tri-lateral crosstalk manner." (PMID 34771621, 2021). "Notably, this therapeutic combination gave rise to a population of tumor-infiltrating CD4+ T cells with high expression of IFN-γ and TNF-α in response to re-stimulation with tumor antigens, suggesting that these cells were potent tumor antigen-specific Th1 cells." (PMID 33777008, 2021). "To determine the role of B7 family molecules and tryptophan degrading enzymes (IDO, TDO) in tumor and stromal cell interactions, we investigated the response of HepG2 cells and MSCs to cytokines commonly produced by infiltrating immune effector cells, such as IFNγ and TNFα." (PMID 34869307, 2021). "TNF-α-mediated signaling in NSCLC cell lines was shown to be favorable for cancer initiation, as TNF-α-induced NF-κB signaling led to the protection from cell death and was shown to have a metastasis-promoting effect associated with tumor recurrence and drug resistance." (PMID 33925297, 2021). "Meanwhile, the selenylated sweet potato polysaccharides could scavenge free radicals much efficiently, and also could inhibit tumor growth, increase the secretion levels of IL-2 and TNF-α but decrease the serum vascular endothelial growth factor (VEGF) level in the murine H22 hepatoma mice model." (PMID 34829068, 2021). "Additionally, contrasting data show that macrophages can exert in vitro cytotoxicity against various tumor cells through distinct mediators, such as NO and TNF-α —these being hallmarks of M1 macrophages—but also arginase, which is a crucial characteristic of M2 macrophages." (PMID 34205330, 2021). "Although TNF was originally identified as a factor that induced necrosis of tumor cells, recent meta-analysis and network meta-analysis has shown that treatment with biological DMARDs (bDMARDs) including TNF-inhibitor did not increase the risk for malignancies." (PMID 34681582, 2021). "Tumor necrosis factor (TNF) is a homotrimeric cytokine which shows direct cytotoxic activity on certain types of cancer cells, stimulates anti-tumor immunity, and may also be active on the tumor endothelium, leading to intravascular blood coagulation or to haemorrhagic necrosis." (PMID 34576184, 2021). "However, the release of cytotoxic cytokines, including INFγ and TNFα, could compensate for the failure of cell contact-dependent tumor cell killing." (PMID 32666260, 2021). "We further demonstrated in mouse model that treatment with B20.4.1.1, the mouse analog of Bevacizumab increased macrophage recruitment to the tumor area and correlated with upregulated TNFα expression in GAMs and increased EC activation, which may be responsible for the failure of AATx in GBMs." (PMID 33853689, 2021). "Finally, the expression of TNF-α in all tumor types was low and uninfluenced by the treatment." (PMID 34205330, 2021). "TAMs could promote tumor angiogenesis and tumor growth by secreting TNF-α." (PMID 33453722, 2021). "In tumor environment, DC-derived exosomes containing TNF, Fas ligand (FasL), and TNF-related apoptosis-inducing ligand (TRaIL) could lead to tumor cell apoptosis and activate natural killer cells via TNF superfamily ligands for enhanced tumor inhibition." (PMID 33868247, 2021).
tumor (continued). "Surprisingly, increasing levels of TNF could be detected in whole lung homogenates by luminex multiplex assay 2 h and 6 h post tumor challenge, suggesting that TNF might be important for the extravasation of the tumor cells." (PMID 33546280, 2021). "Inhibitors of TNFα and IL-1β are currently used in the clinic in the treatment of inflammatory diseases and may have many advantages when introduced to cancer therapy at the stage of tumor diagnosis." (PMID 33806906, 2021). "Although in vitro models (cancer cells/adipocytes) confirmed that phenotype of CAAs may be triggered directly by cancer cells, and some candidate molecules released by tumor cells such as TNF-α, Wnt3a, Wnt5a, and MMP11 have been proposed, the exact mechanism remains elusive." (PMID 33916703, 2021). "Meantime, TNF-α may be involved in inducing tumor cells to die." (PMID 33898412, 2021). "Tumor associated macrophages (TAM) and myeloid-derived suppressive cells (MDSC) in the HCC microenvironment release cytokines, such as IL-6 and tumor necrosis factor (TNF), thereby inducing cancer cell proliferation and inhibiting apoptosis through activation of NF-κB and Stat3." (PMID 34178028, 2021). "Similar to our previous data, loss of TNF in B16-F10 cells did not affect tumor burden." (PMID 33546280, 2021). "Adhesion molecules linked to leukocyte binding are suppressed by angiogenic factors leading tumor ECs to adopt a state known as endothelial anergy where there is a lack of an immune response to the presence of proinflammatory stimuli such as IL-1, TNF-α, and IFNγ." (PMID 34987525, 2021). "Furthermore, exercise could effectively reduce the tumor volume, lower levels of proinflammatory cytokines TNFα, increase the anti-inflammatory cytokine IL-10 by regulating miR-21a-5p expression." (PMID 34099844, 2021). "An excess concentration of TNF reduces the protective abilities of the intestinal epithelium and enhances the processes of intestinal tissue fibrosis, which may contribute to the development of neoplastic diseases." (PMID 33923129, 2021). "Numerous inflammatory mediators such as TNF-α, IL-6, IL-10, IL-23, and transforming growth factor-β (TGF-β) were found to be associated with carcinogenesis and the development of CRC and their effects include pro-tumor, anti-tumor, and double-edge effects in CRC pathogenesis." (PMID 33578830, 2021). "Additionally, TNFR2 is expressed primarily on immune cells including Treg and MDSC, where acute production of TNF-α is associated with Treg expansion and increased infiltration of Treg and MDSC populations in the TME, leading to tumor progression and decreased efficacy of immunotherapies." (PMID 34012451, 2021). "NOS2 is activated through proinflammatory cytokines such as IFNγ, TNFα, IL-1β, and LPS and has been well-characterized to metabolize L-arginine to L-citrulline and cytotoxic nitric oxide (NO; a pro-inflammatory mediator responsible for anti-tumor immune response)." (PMID 33968034, 2021). "Thus, depending on the cellular context, TNF can promote cell death or tumor growth." (PMID 33373873, 2021). "In addition, their findings showed that the treatment of cancer cells with butanol extract of B. adolescentis SPM0212 triggers macrophage activation and significantly enhances the production of TNF-α and NO as two mediators of the immune system with cytotoxic effects on tumor cells." (PMID 33980239, 2021). "Indeed, it was also observed in tumors from the gastrointestinal tract that the tumor-conditioned media could inhibit TNF-α secretion in moDCs." (PMID 34062821, 2021). "The shift towards a pro-inflammatory TIME with increases in TNFα over the first 3 days following pFUS could also be responsible for the increased expression of CD31 on endothelium reflective of immunological stress within both tumor types." (PMID 33801627, 2021). "Besides TNF, lymphocyte‐mediated tumor cell apoptosis also involves cytotoxic TRAIL signaling." (PMID 33484626, 2021).
tumor (continued). "CD40 ligation provides essential activation signals for immune cells, although its function in the promotion or inhibition of tumorigenesis and progression via regulation of TNF alpha (TNFα)‐induced apoptosis, angiogenesis, tumor cell migration and invasion, and chemoresistance is unknown." (PMID 34184409, 2021). "On the other hand, the M2d macrophage subtype that has been linked with the tumor progression is characterized by the extensive production of TNF-α, and PARP poisons may facilitate tumor progression by promoting the activity of tumor-associated macrophages (TAMs)." (PMID 33671709, 2021). "Hence, the expression of TNFR1 and of RIPK1/RIPK3/MLKL proteins by tumor cells, in conjunction with the production of TNFα in the tumor microenvironment, could represent novel biomarkers for cisplatin sensitivity in apoptosis-resistant tumors." (PMID 34490126, 2021). "Importantly, the authors also report that addition of anti-TNFα therapy may also enhance the anti-tumour effects of the PD-1 treatment." (PMID 33423684, 2021). "TNF-α levels in human PC tissues were associated with chemoresistance but not tumor stage." (PMID 34205944, 2021). "Macrophages represent key players in anti-tumor immunity through phagocytosis and antigen presentation, which also actively participate in the production and regulation of immune effector cells, as well as secretion of cytokines (e.g., TNF-α, IL-1, IL-6, and interferon (IFN)-α/β)." (PMID 34845974, 2021). "Thus, the interaction of TNF-α and hCasp12/VC12 may contribute to the activation of the NF-κB pathway associated with tumor cell invasion and metastasis." (PMID 33924755, 2021). "Interestingly, TNFα is able both to stimulate and inhibit tumor growth." (PMID 34885171, 2021). "Moreover, TNF-α-activated mesenchymal stromal cells activate a proinflammatory chemokine signature that recruits neutrophils, which in turn stimulate the initiation of a metastatic reprogramming of tumor cells." (PMID 34064859, 2021). "Therefore, as the tumor necrosis percent may be representative of tumor necrosis factor, we can expect that the presence of tobacco smoke corresponds to elevated tumor necrosis factor expression in the smoking-onset LUSC cohort." (PMID 34439379, 2021). "Recently, it has been reported that a tumor necrosis factor (TNF)/inducible nitric oxide synthase (iNOS)-producing dendritic cell (Tip-DC) may play a pivotal role in the anticancer immune response by activating CD8+ T cells in tumor microenvironments." (PMID 33499256, 2021). "Besides, the tumor-killing functionality of TAMs should also be ideally achieved through various mechanisms, e.g., the phagocytosis of tumor cells, secretion of cytokines (e.g., IFNγ and TNFα), production of inducible nitric oxide synthase, and induction of anti-tumor inflammation." (PMID 34675914, 2021). "Notably, TNFα has been proposed as a mediator of STING-induced tumour EC apoptosis." (PMID 34285232, 2021). "Hence, we tested whether the combined intracellular detection of CD137, TNF, and IFNγ was feasible, and whether the addition of CD107a to the panel enhanced the detection of tumor-specific reactive TILs in vitro." (PMID 34707600, 2021). "Furthermore, tumor‐derived TNF‐α promotes neutrophil activation and neutrophil B7‐H2 expression by the activation of pathways of extracellular signal‐regulated kinase (ERK) and the activation and translocation of phosphorylated transcription factor nuclear factor κB (NF‐κB) into nucleus." (PMID 34185422, 2021). "Furthermore, T cells from tumor-draining LNs produced IFNγ and TNFα even during tumor progression." (PMID 33408092, 2021). "Moreover, the additional anti-tumor mechanism of tramadol was confirmed in vivo by preserving NK cell activity to maintain immune function and decrease the production of pro-inflammatory cytokines such as TNF-α and IL-6." (PMID 34764420, 2021).
tumor (continued). "Furthermore, TGF-β present in the tumor microenvironment has been reported as critical to suppress DC maturation and inhibit their production of pro-inflammatory cytokines such as IL-12 and TNF-α, hampering the activation of T cells." (PMID 34977027, 2021). "Moreover, blocking PD-1 significantly increased the percentage of TNF-α+ ILC2s, further suggesting a novel mechanism by which PD-1 blocking antibody may lead to tumor inhibition by ILC2s in vivo." (PMID 34531874, 2021). "TNF-α was first identified as a potential anti-tumor agent, as it can induce and trigger apoptosis of cancer cells in high doses; however, due to significant toxicities and lack of efficacy, the clinical trials of systemic administration of TNF-α for treating cancer have been disappointing." (PMID 33633307, 2021). "Similarly, curcumin inhibits TNFα-dependent EMT in tumor cells." (PMID 34220337, 2021). "The secretion of the pro-inflammatory cytokines IFN-γ and TNF-α, as shown by AdCAR NK-92 cells co-incubated with the target cell line and a specific bAb, may, additionally, stimulate the endogenous immune system and enhance anti-tumor activity." (PMID 33807875, 2021). "The mechanisms that CTLs and NK cells use to attack tumor cells consist of the secretion of death-inducing effector molecules towards the target cell, most importantly GzB, Pf and FasL, as well as the production of effector cytokines such as tumor necrosis factor." (PMID 34943854, 2021). "Additionally, MYDGF could induce the chemotaxis of macrophages into tumor tissues and promote them releasing inflammatory cytokines, including IL-6 and TNF-α." (PMID 33391471, 2021). "Similarly, cytokine fusion compounds which deliver for instance TNFα or IFNγ to tumor vessels in PNET induce vessel normalization and/or vessel wall inflammation without TLS formation demonstrating the unique opportunities of targeting LIGHT into the tumor microenvironment." (PMID 34122434, 2021). "Furthermore, MYDGF can also promote tumor angiogenesis, induce macrophages to chemotaxis into tumor tissue, and then release various inflammatory cytokines, including IL-6 and TNF-α, which ultimately aggravate inflammation of tumor microenvironment and accelerate HCC progression." (PMID 33391471, 2021). "Flow cytometry analyses of tumor-infiltrating NK cells from sMIClo and sMIChi tumors validated that NK cells from sMIChi tumors had diminished cytotoxic effector function and marked reduction in the capacity to produce anti-tumor cytokines, such as IFNγ and TNFα." (PMID 34294876, 2021). "Therefore, we speculated that pDC-derived TNF-α contributed in part, along with other inflammatory mediators in the tumor microenvironment, to activate the NF-κB pathway." (PMID 33854604, 2021). "Inflamed VAT is a major contributor to the progression of systemic inflammation by secreting numerous pro-inflammatory cytokines including IL-1β, IL-6, and TNF-α into systemic circulation, which could have a remote effect leading to an increase in tumor aggressiveness." (PMID 35010352, 2021). "As an early effect, TNF-α induces an increased uptake of the simultaneously administered alkylating agent into the tumor under ILP, accompanied with its important antiangiogenetic effects, leading to delayed selective destruction of tumor-associated vessels and subsequent tumor regression." (PMID 34206128, 2021). "Indeed, when present at low concentrations, TNF-α may sustain tumor promotion via the regulation of ROS and reactive nitrogen species (RNS) signaling, oncogene activation, and DNA damage." (PMID 34205944, 2021). "However, the likely outcome of this is unknown given the fact that tumor or microenvironment derived TNF-α can have paradoxical tumor promoting and inhibiting roles." (PMID 33946744, 2021). "However, locoregional drug delivery systems have shown that TNF alone or combined with supplementary pharmacological agents could be a possible approach for tumor therapy by inducing tumor sensitivity to the treatment." (PMID 33707603, 2021).